RN7SL329P (RNA, 7SL, cytoplasmic 329, pseudogene)
Gene: Miscellaneous RNA gene on chromosome 8 (125,270,604 to 125,270,902, forward strand). Ensembl gene ENSG00000242170.
Homologues: Orthologues: chimpanzee Metazoa_SRP (96% identical), macaque Metazoa_SRP (95% identical). Paralogues in human: RN7SL2 (84% identical), RN7SL1 (83% identical), RN7SL3 (82% identical), RN7SL30P (82% identical), RN7SL732P (80% identical), RN7SL479P (80% identical), RN7SL665P (80% identical), RN7SL804P (80% identical), RN7SL147P (79% identical), RN7SL145P (79% identical), RN7SL239P (79% identical), RN7SL113P (79% identical), and 705 more.